HOMER1 (homer scaffold protein 1)
Description:
Postsynaptic density scaffolding protein. Binds and cross-links cytoplasmic regions of GRM1, GRM5, ITPR1, DNM3, RYR1, RYR2, SHANK1 and SHANK3. By physically linking GRM1 and GRM5 with ER-associated ITPR1 receptors, it aids the coupling of surface receptors to intracellular calcium release. May also couple GRM1 to PI3 kinase through its interaction with AGAP2. Isoform 1 regulates the trafficking and surface expression of GRM5. Isoform 3 acts as a natural dominant negative, in dynamic competition with constitutively expressed isoform 1 to regulate synaptic metabotropic glutamate function. Isoform 3, may be involved in the structural changes that occur at synapses during long-lasting neuronal plasticity and development. Forms a high-order complex with SHANK1, which in turn is necessary for the structural and functional integrity of dendritic spines (By similarity). Negatively regulates T cell activation by inhibiting the calcineurin-NFAT pathway. Acts by competing with calcineurin/PPP3CA for NFAT protein binding, hence preventing NFAT activation by PPP3CA.
Synonyms: SYN47; Ves-1; HOMER-1B; HOMER; HOMER1A; HOMER1B; HOMER1C
Tractability: Antibody: its Gene Ontology location is reachable by antibodies, with medium confidence. PROTAC: ubiquitination databases record sites on it; its protein half-life has been measured.
Safety:
Unwanted effects reported when the protein is acted on. In parentheses: how it was acted on, where the effect was seen, and who reports it.
adverse reactions, hallucinations and dyskinesia (source: ClinPGx)
Gene: Protein-coding gene on chromosome 5 (79,372,636 to 79,514,565, reverse strand). Ensembl gene ENSG00000152413.
Subcellular location: Cytoplasm; Postsynaptic density; Synapse; Cell projection, dendritic spine
Subcellular location (Human Protein Atlas): Cytosol
Pathways (Reactome):
Neuronal System: Neurexins and neuroligins
Gene Ontology:
Molecular function: protein binding; transmembrane transporter binding; G protein-coupled glutamate receptor binding; signaling adaptor activity
Biological process: response to calcium ion; chemical synaptic transmission; G protein-coupled glutamate receptor signaling pathway; phospholipase C-activating G protein-coupled glutamate receptor signaling pathway; positive regulation of signal transduction; protein tetramerization; regulation of dendritic spine maintenance; regulation of store-operated calcium entry; regulation of synaptic transmission, glutamatergic; regulation of calcium ion import
Cellular component: cytoplasm; cytosol; dendrite; neuron spine; plasma membrane; postsynaptic density; apical part of cell; axon; costamere; dendritic spine; glutamatergic synapse; membrane; neuron projection; postsynapse; postsynaptic cytosol; synapse; Z disc
Genetic constraint (gnomAD): Loss-of-function variants: 2 observed, 34.02 expected, observed/expected ratio (o/e) 0.0588, 90% interval 0.023 to 0.19. The upper end of that interval is the gene's LOEUF score, 0.19, which puts it in group 1 of 6, group 1 being the genes least tolerant of losing a copy. Missense variants: 180 observed, 341.25 expected, observed/expected ratio (o/e) 0.53, 90% interval 0.47 to 0.6. Synonymous variants: 118 observed, 123.28 expected, observed/expected ratio (o/e) 0.96, 90% interval 0.82 to 1.12.
Homologues: Orthologues: dog HOMER1 (99% identical), mouse Homer1 (99% identical), pig HOMER1 (98% identical), rabbit HOMER1 (98% identical), rat Homer1 (97% identical), tropical clawed frog homer1 (92% identical), macaque HOMER1 (90% identical), guinea pig HOMER1 (86% identical), chimpanzee HOMER1 (85% identical), zebrafish homer1b (76% identical). Paralogues in human: HOMER3 (52% identical), HOMER2 (51% identical).
Diseases named in the same sentence as HOMER1 in open-access papers:
HOMER1 is named in the same sentence as 94 diseases in open-access papers, as found by Europe PMC text mining. Sharing a sentence is not in itself a finding about the gene and the disease. The quoted sentences say what the papers report.
schizophrenia (30 papers, 2012 to 2026). A major psychotic disorder characterized by abnormalities in the perception or expression of reality. "Homer is a family of proteins located at the PSD associated with schizophrenia, as demonstrated by genetic clinical and preclinical studies investigating the Homer1 gene." (PMID 36983018, 2023). "HOMER1 variants are associated with neuropsychiatric disorders, such as schizophrenia, Alzheimer’s disease, addiction, pain, intellectual disability, and traumatic brain injury." (PMID 37511534, 2023). "A number of clinical and preclinical reports have implicated Homer1 in the pathophysiology of depression, schizophrenia and addiction." (PMID 24465821, 2014). "Homer1 polymorphisms have been associated with schizophrenia and cocaine addiction and Homer1 knock-out mice exhibit a behavioral phenotype resembling psychotic disorders, as well as Homer2 proteins have been implicated in regulating addiction to cocaine in animal models." (PMID 29321734, 2017). "A recent study identified reduced expression of a circRNA derived from HOMER1 gene (circHOMER1) in the DLPFC of patients with schizophrenia and bipolar disorder." (PMID 39966624, 2025). "In postmortem hippocampal CA1 from patients with schizophrenia, a decrease in long Homer1 isoforms and an increase in the short isoform Homer1a have been observed." (PMID 40715999, 2025). "We tested candidate genes on a cohort of schizophrenia-associated hiPSC-derived neurons and found blunted expression profiles for COX7A2, GRID2 and HOMER1 using quantitative PCR." (PMID 29691375, 2018). "A recent study observed a decrease in long Homer1 isoforms but increased short-form Homer1a in postmortem hippocampal CA1 from patients with schizophrenia, suggesting that these patients had a higher ratio of short to long Homer1 proteins in this region." (PMID 29238619, 2017). "A number of genetic knockout studies (mGluR5, Norbin, Homer1 etc.)continue to lend support to a role of mGluR5 in the pathology of schizophrenia, providing impetus to explore the regulation of mGluR5 beyond total mGluR5 protein and mRNA levels." (PMID 24472577, 2014). "For instance, a dysregulation in protein levels of several molecular components of dendritic spines, including postsynaptic density 95 (PSD-95), NMDAR subunit GluN1, spinophilin, and Homer 1, has been detected in multiple brain regions of patients affected by schizophrenia." (PMID 36901803, 2023). "At least one polymorphism in the Homer1 sequence, i.e., rs2290639, has been significantly associated with psychotic symptoms measured by PANSS and response to four-week antipsychotic treatment in a population of schizophrenia patients." (PMID 36979877, 2023). "HOMER1 knockout (KO) mice show behavioral abnormalities related to psychiatric disorders, and HOMER1 has been associated with psychiatric disorders such as addiction, autism disorder (ASD), schizophrenia (SZ), and depression." (PMID 33398084, 2021). "HOMER1, MAGI2, SLC1A3, NRG3 were associated with schizophrenia." (PMID 32993537, 2020). "Homer-1 knockout mice are viable but they display behavioural and neuronal defects and Homer signalling is found to be altered in several neurological disorders such as Schizophrenia, Alzheimer's disease, neuropathic pain, epilepsy and Fragile X syndrome." (PMID 22558223, 2012). "Rare variants and hypermethylation of the Arc gene, as well as, polymorphisms in Homer1 gene, were found in patients affected by schizophrenia, correlated to both positive and negative symptoms of psychosis, and associated with treatment response to antipsychotic drugs." (PMID 41258376, 2026). "Homer1 plays an important role in working memory, executive functions, and regulation of cortical hyperexcitability, and it has been hypothesized to play a pivotal role in dopamine-glutamatergic neurotransmission, relevant in the pathogenesis of schizophrenia." (PMID 36831241, 2023).
schizophrenia (continued). "Recently, deficits in circ-Homer1 in both the prefrontal cortex and IPSC-derived neuronal cultures were documented from patients with schizophrenia and bipolar disorder." (PMID 36463316, 2022). "In turn, Homer1-knock-out animals, in which a direct mGluRI-NMDAR link is absent, exhibit a wide spectrum of abnormalities that are consistent with schizophrenia symptoms, thus suggesting Homer as an actor preventing schizophrenia development." (PMID 30282730, 2018). "While the candidate genes used to construct this network were selected using evidence for disease implication derived from two different approaches, the network includes many additional genes of potential relevance to schizophrenia (e.g., GRIA2, GRIN1, GRIN2B, HOMER1, PICK1, and SNAP25)." (PMID 25484875, 2014).
depression (28 papers, 2011 to 2025). "The Homer1 gene is implicated in the pathogenesis of major depression through genome-wide association as well as neuroimaging studies." (PMID 28503137, 2017). "Further, specificity tests of genetic associations could be extended by accounting for other candidate genes implicated in depression risk (e.g., HOMER1, TPH, DRD4, COMT)." (PMID 24312122, 2013). "The interaction between mGluR5 and Homer1 proteins further underscores the receptor's role in depression." (PMID 40964490, 2025). "Infection-related downregulation was also observed for several synaptic proteins previously identified in genetic studies of neuropsychiatric disorders like bipolar disorder (neurocan), major depression (Homer-1; Piccolo), or autism (Shank2)." (PMID 30068357, 2018). "Animal evidence and genetic studies suggest that HOMER1 (homer homolog 1) is involved in the etiology of suicidal behavior and major depression disorder (MDD)." (PMID 27386253, 2016). "Moreover, DNA methylation of CpG sites around the binding sites for CRE in Homer1 promoter results in major depressive disorder." (PMID 36590248, 2023). "Some antidepressant treatments suppress depression-like behaviors by modulating Homer1 expression." (PMID 35610650, 2022). "PSD proteins, such as PSD-95, CamKII, Homer 1, and Shank3 may also be involved in the development of depressive disorders." (PMID 36232725, 2022). "Interestingly, it has been described that in fear conditions or depression there exists an epigenetic modulation of HOMER1 transcription regulation." (PMID 34502114, 2021). "HOMER protein homolog 1 (HOMER1) is a well-established regulator of synaptic plasticity and neuronal excitability, which has been linked to a plethora of psychiatric disorders, including SCZ and depression." (PMID 31988434, 2020). "A recent GWAS analysis also suggests that HOMER1 plays a role in the etiology of major depression." (PMID 21785720, 2011). "Thus, SSD may alleviate depression-like behaviors in CUMS-exposed rats by regulating the Homer1-mGluR5 and mTOR signaling pathways." (PMID 35610650, 2022). "qPCR results showed that knockdown of Homer1 improved the expression of inflammation‐related markers IL‐1β, TNF‐α, IL‐10, and depression‐related markers ERCCL2, SLC6A4, and GAD1 in primary neurons, both in the PTSD group and in the TBI+Hcort group." (PMID 39665190, 2025). "Homer1 mRNAs are well-established effectors of neuronal excitability and synaptic plasticity, including SCZ and depression." (PMID 31988434, 2020). "Our results indicating normal interactions between SHANK3 and Homer1 in Dlgap1 KO mice is consistent with the absence of any depression-related phenotype in these mice, including lack of effects in the FST and sucrose preference test." (PMID 29396406, 2018). "Furthermore, genetic studies found that homer scaffold protein 1 (Homer1) was reduced in FSS mice and that Homer1 knockout mice exhibited depression-like behavior, implying that FSS mice have some, if not all, of the depressive status." (PMID 36835151, 2023).
autism (11 papers, 2012 to 2025). Persistent deficits in social interaction and communication and interaction as well as a markedly restricted repertoire of activity and interest as well as repetitive patterns of behavior. "Eight differentially expressed genes (DEGs) were identified exclusively in this group, including Homer1 and Zswim6, both of which are listed as high-confidence autism risk genes in the SFARI Gene database." (PMID 40801633, 2025). "High genetic variations in SHANK3 were identified in the Autism Genetic Resource Exchange sample, together with HOMER1 variants." (PMID 34627165, 2021). "HOMER1, which is an autism risk gene, is considered an important component of the postsynaptic density (PSD) proteins network." (PMID 31744938, 2019). "Rare, potentially deleterious HOMER1 variants identified uniquely in the autism population affected functionally important protein regions or regulatory sequences and co-segregated closely with autism among children of affected families." (PMID 22558107, 2012). "The association of rare functional variation in Homer1 with genetic risk for autism identified in this study provides further insight into the emerging role of synaptic dysfunction in autism pathogenesis." (PMID 22558107, 2012). "Homer1 thus provides a novel link between autism-associated gene products that operate downstream of mGluRs and those that interact with Shank proteins, most notably neuroligins." (PMID 22558107, 2012). "To assess further the pathogenicity of the rare, potentially disruptive HOMER1 variants uniquely identified in the autism population, we analyzed co-segregation of these variants with autism." (PMID 22558107, 2012). "A recent report showed that homer 1 is a risk gene in autism, thus validating our novel finding." (PMID 23803181, 2013). "In addition, our analysis identified HOMER1, which encodes a postsynaptic density-localized scaffolding protein that interacts with Shank3 to regulate mGluR activity, as a novel autism-risk gene." (PMID 22558107, 2012). "Pathway analysis of differentially expressed genes in the ASD group identified molecular networks linked to nervous system disorders, synaptic plasticity, and the canonical autism signaling pathway, involving key nodes such as Mapk3 and Homer1." (PMID 40801633, 2025). "For example, a study comprised of a population diagnosed with non-syndromic autism identified a significant number of genes involved in the mGluR5 pathway including Homer1." (PMID 26929812, 2016). "The observed reduction in homer 1 expression in BA9 of adults with autism may have functional consequences resulting in altered glutamatergic expression and cognitive deficits associated with both FXS and autism." (PMID 23803181, 2013). "The fourth gene displaying a significant enrichment of autism-associated rare SNVs, HOMER1, has not previously been implicated in autism." (PMID 22558107, 2012). "Although significant enrichment of rare, potentially disruptive variants in AGRE samples relative to controls was limited to the TSC1, TSC2, SHANK3, and HOMER1 genes, individual variants in additional genes suggest a role for the Ras/ERK cascade in autism susceptibility." (PMID 22558107, 2012). "Moreover, different animal models of autism have indicated that Homer1 and Homer1a function may be dysregulated in these models." (PMID 26929812, 2016). "Taken together, the results of current postmortem studies provide novel evidence that targets of FMRP and mGluR5 signaling (RAC1, homer 1, APP, and STEP) display altered expression in the cerebellar vermis and BA9 of people with autism." (PMID 23803181, 2013).
autism (continued). "The altered expression of proteins that may contribute to altered dendritic protein translation (homer 1), altered dendritic morphology (APP and RAC1), and receptor subunit expression (STEP), potentially contribute to the cognitive and behavioral impairments associated with autism and FXS." (PMID 23803181, 2013). "At the level of individual pathway genes, we identified a significant excess of SNVs in the autism population for the TSC1, TSC2, SHANK3, and HOMER1 genes (P<0.05)." (PMID 22558107, 2012). "We did not observe alterations in levels of homer 1 or APP 88 kDa in the cerebellar vermis of adults with autism and there were no significant changes for any of the proteins in the cerebellar vermis of children with autism." (PMID 23803181, 2013). "Probands from two of these families carried a second rare variant in addition to the HOMER1 variant, but these other variants did not co-segregate with the autism phenotype (HOMER1 c.290C>T and SHANK3 c.898C>T; HOMER1 c.195 and PIK3CA c.2294+19C>T)." (PMID 22558107, 2012).
Alzheimer disease (8 papers, 2012 to 2023). A progressive, neurodegenerative disease characterized by loss of function and death of nerve cells in several areas of the brain leading to loss of cognitive function such as memory and language. "Recent studies show that circular RNA derived from HOMER1 (circHOMER1) expression is altered in some Alzheimer’s disease (AD) brain regions." (PMID 34502114, 2021). "We validated a circRNA in RTN4, a gene inhibiting axonal sprouting and modulating Alzheimer’s disease progression in a mouse model and one of two predicted circRNAs in HOMER1, a gene that is involved in synaptic activity and various neurological disorders." (PMID 28842720, 2017).
cognitive deficits (7 papers, 2013 to 2025). "Both group 1 mGluR function and Homer 1 expression have been associated with stress-induced cognitive deficits, and anxious behaviors are exacerbated by aging in the mGluR5−/− mice." (PMID 24847259, 2014).
Anxiety (6 papers, 2016 to 2020). Intense feelings of nervousness, tension, or panic often arise in response to interpersonal stresses. "Indeed, genetic deletion of H1 (an activity-inducible isoform of Homer1) restored regular mGluR5-long Homer association in the Fmr1 KO and corrected much of the mGluR5 dysfunction as well as behavioral phenotypes, including anxiety and audiogenic seizures." (PMID 31035599, 2019). "Accordingly, Homer 1 KO mice exhibit an exacerbated behavioral response to stressors because, in the absence of Homer 1, there is no buffering response to anxiety." (PMID 28331639, 2017). "In stark contrast, the anxiety-like behavior exhibited by Homer1a-/- herein was indistinguishable from that of wild-type mice, although Homer1+/- mutants did exhibit signs of hypo-anxiety on the elevated plus maze." (PMID 29163080, 2017).
bipolar disorder (6 papers, 2018 to 2026). A disorder of the brain that causes unusual shifts in mood, energy, activity levels and the ability to carry out day-to-day tasks. "Genetic variation in the HOMER1 locus near a distal enhancer region (rs6865469, p = 1.65e–08) is significantly associated with bipolar disorder." (PMID 39966624, 2025).
brain ischemia (5 papers, 2018 to 2022). Diminished or absent blood supply to the brain caused by obstruction (thrombosis or embolism) of an artery resulting in neurologic damage. "Homer scaffolding protein 1 (Homer1) plays a protective role in ischemic encephalopathy and neurodegenerative diseases." (PMID 35287697, 2022). "Hence, compared to the control group, OGD markedly induced immediate early genes such transcription factors (Fosb, Nr4a, Maff, Erg1, Erg2), signaling molecules DUSP and others such as Homer 1 and bdnf in rat models of brain ischemia." (PMID 29523072, 2018).